PRL (prolactin)
Diseases named in the same sentence as PRL in open-access papers (continued):
Sharing a sentence is not in itself a finding about the gene and the disease.
breast cancer (continued). "Finally, high mammographic density, which is perhaps the strongest risk factor for non-familial breast cancer apart from age and gender, has been associated with higher PRL levels in some but not all studies." (PMID 20736944, 2010). "In such a case, the joint actions of prolactin, (induced by suckling) and progesterone (from corpus luteum of the second pregnancy) would initiate, in the beginning of second pregnancy, abnormal cellular changes owing to the potential for breast cancer development." (PMID 19738607, 2009). "Interaction of Src with numerous breast cancer-associated growth factors and signalling pathways, such as prolactin, EGFR, ERK1/2, PI3-kinase, and oestrogen receptor, supports the notion that Src activity contributes to the growth and survival of breast cancer cells." (PMID 19513066, 2009). "In addition, autocrine/paracrine prolactin appears to be a survival factor in this subpopulation of breast cancer cells and is induced by treatment with doxorubicin or paclitaxel, as treatment with the PRLR antagonist Δ1–9 potentiates the efficacy of such drugs." (PMID 18681966, 2008). "If autocrine prolactin is preferentially produced by a cytotoxic-resistant putative breast cancer stem cell, then the rational combination of cytotoxic agents and Δ1–9 may improve outcomes in breast cancer therapy." (PMID 18681966, 2008). "Early studies in animals first demonstrated that prolactin could induce spontaneous mammary tumors." (PMID 18053149, 2007). "However, a new study suggests that prolactin may play a larger rolein the development of human breast cancer, more than previously thought." (PMID 16882534, 2006). "Indeed, several laboratories have since demonstrated the synthesis of prolactin in breast cancer cells and normal breast tissue, raising the possibility that prolactin may act in an autocrine/paracrine manner within the mammary gland." (PMID 15213724, 2004). "Indeed, the role of prolactin in rodent mammary cancer soon became clear." (PMID 15213724, 2004). "Assessing prolactin concentrations within breast tumours may allow us to predict the response to current chemotherapeutic drugs; in addition, it supports the use of effective prolactin antagonists, since they may provide a better, more effective therapeutic intervention for some breast cancers." (PMID 15213724, 2004). "Therefore, the addition of a somatostatin analogue and an anti-prolactin may potentially enhance the efficacy of anti-oestrogens in the treatment of breast cancer owing to favourable endocrine and possible direct anti-tumour effects." (PMID 9459155, 1998). "The influence of prolactin (PRL) and melatonin on breast cancer represents a complex interplay of hormonal signaling with significant implications for tumor progression and therapeutic strategies." (PMID 41370498, 2025). "While PRL has been shown to regulate Hippo pathway leading to pigeon crop epithelial cell proliferation, our study showed that PRL/PRLR/Jak2 pathway results in Hippo pathway activation and nuclear exclusion of YAP in mammary epithelial and breast cancer cells." (PMID 40157909, 2025). "We further employed a preclinical model of breast cancer and defined PRL and VPF by promoting differentiation and effectively suppressing tumor cell growth as a potential combination therapeutic approach in breast cancer." (PMID 40157909, 2025). "Our study highlights a potential combination therapeutic modality based on PRL and YAP inhibitors or PRL and anti-CCN2 antibodies in breast cancer." (PMID 40157909, 2025). "To elucidate the role CCN2 in regulating/altering PRL/PRLR effects in mammary and breast cancer cells, we first generated CCN2 physical interaction gene network." (PMID 40157909, 2025). "Together, our study emphasises the differentiation and anti-tumorigenic role of PRL in breast cancer by blocking the YAP-CCN2 oncogenic pathway providing prognostic and therapeutic strategies in breast cancer with also potential impact in other cancer types." (PMID 40157909, 2025).
breast cancer (continued). "Despite this strong evidence, the interplay between PRL signaling, A/B polarity proteins, and the Hippo-YAP-CCN2 pathway in mammary and breast cancer is still to be established." (PMID 40157909, 2025). "Having demonstrated a molecular antagonism between PRL/PRLR pathway and YAP-CCN2 pathway in mammary and breast cancer cells, we next sought to determine the clinical impact of this antagonism regarding breast cancer prognosis and potential therapeutic value." (PMID 40157909, 2025). "Besides, activation of PRLR pathway by PRL could desensitize breast cancer cells to tamoxifen." (PMID 38898487, 2024). "For instance, the involvement of E2, serotonin, and prolactin with pathogens such as HPV and C. trachomatis in carcinogenesis is well-established not only in CC but in breast cancer as well." (PMID 38732382, 2024). "Experimental studies have shown that phosphorylation of STAT5 regulates the biological functions of prostate and breast cancer cells, and the JAK2/STAT5 cascade appears to be the only pathway activated by PRL in prostate." (PMID 38341429, 2024). "Altogether, our current data provide insight into the mechanism of PRL- and PAK1-stimulated EMT of breast cancer cells." (PMID 38660565, 2024). "Thus, it is unclear whether the lack of an association is due to lack of a significant increase in prolactin levels, or if prolactin levels were increased but did not result in an increased risk of incident breast cancer." (PMID 38595824, 2024). "It is particularly interesting because we have previously shown that PRL-activated pTyr-PAK1 induces secretion of MMP-1 and MMP-3 in the breast cancer cells grown in 3D collagen IV." (PMID 38660565, 2024). "As CD44 was upregulated by prolactin, blocking CD44 in mammary cancer cells would therefore inhibit iron transport, mediated through the CD44." (PMID 39201626, 2024). "PRL in the mammary gland stimulates tissue profiling, development, and maturation, and increased PRLR expression has been observed in human breast cancer cells." (PMID 36833950, 2023). "In cell line-based assay involving breast cancer cells (MCF-7 and T47D), it has been found that the PRL/PRLR triggers EGFR2 phosphorylation (tyr1221 and 1222) via JAK2, activating the downstream PI3K/AKT signaling." (PMID 37415164, 2023). "Conversely, among postmenopausal women, prolactin was similarly associated with breast cancer risk regardless of pSTAT5 expression or expression of PRLR or pJAK2, suggesting that this pathway may not be the sole or even primary mechanism of action in this population." (PMID 36882838, 2023). "During mammary cell growth, prolactin suppresses BCL6 expression through a STAT5A-related mechanism, suggesting that loss of prolactin-STAT5A signaling and concomitant increases of BCL6 may constitute a regulatory switch and facilitate undifferentiated histology and poor prognosis of breast cancer." (PMID 38124049, 2023). "PRL can initiate phosphorylation of HER2 in SKBR3 and BT474 breast cancer cells in vitro and in a murine MMTV-neu-derived tumor ex vivo." (PMID 35784527, 2022). "Mouse PRL has little activity at the human PRLR, which has complicated experimental study of breast cancers in vivo." (PMID 35784527, 2022). "PRL and estrogen cooperatively induce phosphorylation of ERK1/2 and enhance prolonged activation of AP-1 in breast cancer cells." (PMID 36187116, 2022). "Studies from our lab and others in T47D and MCF-7 breast cancer cells have shown that the PI3K/AKT and RAF/MEK/ERK pathways are activated in parallel following PRL treatment, which leads to profound cell proliferation and survival." (PMID 36187116, 2022). "PRL/PRLR and E2/ER synergistically can regulate the gene expression and proliferation of breast cancer cells." (PMID 36187116, 2022). "Apart from the signalling interaction between ER and PRL pathway, the oestradiol–ER complex has been reported to transcriptionally upregulate both prolactin and PRLR in breast cancer." (PMID 35448537, 2022).
breast cancer (continued). "Studies from our lab and others in T47D and MCF-7 breast cancer cells have shown that PI3K/AKT and RAF/MEK/ERK pathways are activated in parallel following PRL treatment, which leads to profound cell proliferation and survival." (PMID 34572912, 2021). "Immunohistochemical studies also confirmed the overexpression of PRLR, a prolactin (PRL) transmembrane receptor, interacting with PRL to activate downstream signaling in breast cancer." (PMID 34436026, 2021). "PRL/PRLR can substantially promote migration and invasion of T47D breast cancer cells by activating alternate downstream effectors like TEC and NEK3 kinases, leading to cytoskeletal and focal adhesion rearrangements necessary for cell adhesion and migration." (PMID 34572912, 2021). "The effect of PRL stimulates the expression and phosphorylation of c‐Src and FAK in breast cancer cells and enhances the movement of breast cancer cells." (PMID 34651424, 2021). "PRLR signaling enhances breast cancer cell motility by regulating actin cytoskeleton rearrangement which involves phosphorylation of c-SRC, moesin, and FAK kinases by PRL." (PMID 34572912, 2021). "The study showed that PRL inhibited the expression of BCL6 and upregulated the expression of miR‐339‐5p in breast cancer cells." (PMID 34651424, 2021). "Prolactin receptor (PRLR) and epidermal growth factor receptor (EGFR/ERBB) signaling pathways activated by prolactin (PRL) and epidermal growth factor (EGF), have a major role in the mammary gland development and in the etiology of breast cancer, respectively." (PMID 34572912, 2021). "While PRL tends to be elevated in the serum of breast cancer patients, breast cancer cells also synthesize PRL locally as an autocrine/paracrine growth factor and overexpress PRLR to utilize PRL to promote their growth." (PMID 34077462, 2021). "The expression levels of PRL and PRLR in breast cancer cells and breast cancer tissues are elevated in most ER+ and ER− tumours." (PMID 34651424, 2021). "PRL and EGF via their cognate receptors synergistically induce MEK/ERK1/2 and PI3K/AKT pathways which promote proliferation, survival, and invasion of breast cancer cells." (PMID 34572912, 2021). "The activation of the Vav family is related to prolactin (PRL) receptor activation, which contributes to the development of human breast cancer." (PMID 32294979, 2020). "In summary, our data reveal an unforeseen PR-B isoform-specific regulatory action on the cross-talk between prolactin and FASN signaling in luminal breast cancer cells." (PMID 33335078, 2020). "Prolactin (PRL) and testosterone were measured in 5000 and 5786 breast cancer patients, with 15.7% and 10.7% of patients being above or below the reference range, respectively." (PMID 30761775, 2019). "Our syngeneic model allows examination of the behavior of ERα + mammary cancers, including metastasis, permitting us to demonstrate potent interactions between the features of the ECM and PRL that drive aggression in vivo." (PMID 28103936, 2017). "PRL and the PRLR enhanced the endogenous capacity of the breast cancer cells to directly induce the differentiation of osteoclasts via production of soluble factors and also contributed to their osteolytic ability." (PMID 27782069, 2016). "In these studies we also found ERBB2/HER2, a member of epidermal growth factor receptor family which is overexpressed in about 10% of the ER+ breast cancers phosphorylated and activated by JAK2 induced by PRL through PRLR." (PMID 27564112, 2016). "Activation of the canonical PRL signal mediator, STAT5, is a positive prognostic factor in breast cancer that predicts sensitivity to anti-estrogen therapies and favorable outcomes." (PMID 27344177, 2016). "We demonstrate a distinct reduction in PRL-induced FAK auto-phosphorylation in T47D and TMX2-28 breast cancer cells overexpressing wild-type PAK1 (PAK1 WT) when compared to cells overexpressing either GFP or phospho-tyrosine-deficient mutant PAK1 (PAK1 Y3F)." (PMID 27542844, 2016).
breast cancer (continued). "We demonstrate here that tyrosyl phosphorylation of PAK1 in response to PRL regulates PTP-PEST-dependent FAK dephosphorylation, resulting in augmented breast cancer cell migration and invasion and proposed the mechanism explaining these findings." (PMID 27542844, 2016). "To distinguish the impacts of matrix stiffness and ligand density on PRL signals in breast cancer cells, we examined PRL-induced signaling in ERα+, PRLR+ breast cancer cell lines cultured on well-characterized polyacrylamide hydrogels coated with collagen-I." (PMID 27344177, 2016). "Several studies have demonstrated that it is dysregulated in some cancers such as breast cancer (BC), prolactin (PRL) tumors, and colorectal cancer; however, the precise role of ADAMTS6 in tumor development and the underlying mechanisms is unknown." (PMID 27542224, 2016). "Taken together, these data suggest that PRL-mediated pTyr-PAK1 is important in regulating the dynamic activation of FAK and subsequent breast cancer cell migration and invasion." (PMID 27542844, 2016). "We recently discovered that breast cancer cells that migrated to the bone carry the PRL-receptor (PRLR) and that PRL signaling to breast cancer cells advances osteolytic osteoclast differentiation via the production of a soluble factor that modulates the bone." (PMID 27782069, 2016). "Here we examined the effect of matrix density on 17β-estradiol (E2) activity and PRL/E2 interactions in two well-characterized, ERα+, PRLR+, luminal breast cancer cell lines cultured in defined 3D compliant and stiff collagen-I matrices." (PMID 25607819, 2015). "The main result of this work is that PRL increases T47D, ZR75-1, and MCF-7 breast cancer cell movement by inducing structural changes in the cytoskeleton." (PMID 26733941, 2015). "Most physiological PRL actions on the mammary gland are mediated through the JAK2/STAT5 pathway, and in breast cancer, activated STAT5 predicts sensitivity to estrogen targeted therapies and favorable clinical outcomes." (PMID 25607819, 2015). "Prolactin is able to recruit signaling intermediates such as c-Src that are upstream controllers of PI3K and focal adhesion kinase (FAK) in breast cancer cells." (PMID 26733941, 2015). "Remarkably, PRL induces the expression of prolactin-inducible protein (PIP), a component of milk that is widely expressed in breast cancer (BC) and prostate cancer (PC) promoting cancer cell growth and proliferation." (PMID 26691922, 2015). "In these systems, PRL enhances estrogen-induced growth of T47D and MCF-7 breast cancer cells, augments estrogen-regulated transcriptional activity, and prolongs signaling." (PMID 25607819, 2015). "In the same context, PRL/PRLR signaling has the ability to promote progression and invasion in breast cancer through independent pathways to JAK2/STAT5, such as c-Src, FAK and MAPK." (PMID 26346346, 2015). "Although a vast body of evidence from animal, in vitro, and epidemiological studies strongly supports the involvement of prolactin in breast cancer development, the complex and diverse biological and molecular mechanisms through which prolactin may increase risk of breast cancer are not clear." (PMID 25887963, 2015). "The current investigation examines the effect of PRL and STAT-mediated signaling on the transcriptional regulation of LKB1 expression in human breast cancer cells." (PMID 24913037, 2014). "MDA-MB-231, MCF-7, and T47D human breast cancer cells, and CHO-K1 cells transiently expressing the PRL receptor (long form), were treated with 100 ng/ml of PRL for 24 hours." (PMID 24913037, 2014). "Because T47D cells express high endogenous levels of the PRLR LF, but do not exhibit increases in LKB1 mRNA or protein following treatment with PRL, we evaluated the responsiveness of the LKB1 promoter to PRL in this breast cancer cell line." (PMID 24913037, 2014).
breast cancer (continued). "T47D breast cancer xenotransplants in mice displayed variable acidosis (pH 6.5 to 6.9) and tumor regions with elevated GLUT1 displayed resistance to exogenous prolactin despite unaltered levels of prolactin receptors and Stat5." (PMID 24004716, 2013). "A similar result has been reported in breast cancer cell lines T-47D, MCF-7 and Hs578T, showing that PRL has the ability to prevent breast cancer cells from undergoing apoptosis after the treatment with C2-ceramide." (PMID 24148306, 2013). "Therefore it is possible that chronic modest increases in baseline circulating prolactin levels associated with the use of high inhibitor SSRIs may not exceed the threshold necessary to promote breast cancer development." (PMID 23227451, 2012). "Therefore higher levels of prolactin secreted by the pituitary gland secondary to an SSRI-mediated increase in serotonin may not represent the most relevant route of prolactin exposure at the tissue level in relation to breast cancer etiology." (PMID 23227451, 2012). "We genotyped 8 PRL and 20 PRLR tag SNPs in 1965 breast cancer cases and 2229 matched controls, aged 20-74, and living in Warsaw or Łódź, Poland." (PMID 21470416, 2011). "PRL enhances fatty acid β-oxidation by stimulating CPT1 expression and/or activity in MCF-7 and MDA-MB-231 breast cancer cells." (PMID 21294903, 2011). "A 24 hr incubation with 100 ng/ml of recombinant human PRL significantly increased CPT1A mRNA levels by 1.8- and 1.6-fold in MCF-7 and MDA-MB-231 breast cancer cells, respectively (p < 0.0001 and p < 0.001, respectively) compared to untreated controls." (PMID 21294903, 2011). "Recent studies have begun to link genetic variations in the genes for PRL and the prolactin receptor (PRLR) and breast cancer." (PMID 21276249, 2011). "In the current study, we have shown that PRL enhances both the expression and activity of CPT1, the rate-limiting enzyme of mitochondrial long-chain fatty acid β-oxidation, in breast cancer cells in vitro." (PMID 21294903, 2011). "Similar to the published results of Weaver and Silva in breast cancer cells, we also observed Brk-mediated regulation of p-STAT5 in vitro, but only in prolactin-treated (5 to 30 minutes) cells." (PMID 21923922, 2011). "We show here that PRL enhances the expression and/or activity of CPT1 via activation of the AMPK pathway in breast cancer cells." (PMID 21294903, 2011). "In marked contrast, in both MCF-7 and MDA-MB-231 breast cancer cells in which CPT1A was knocked down, PRL increased enzyme activity by 10 and 17%, respectively, although levels were not restored to baseline (reflected by treatment with vehicle only)." (PMID 21294903, 2011). "Prolactin therefore induces both the expression of HSP90A mRNA and increases HSP90α protein in breast cancer cells." (PMID 19014541, 2008). "We sequenced the coding regions of PRL and PRLR in 95 advanced breast cancer cases (19 of each racial/ethnic group) to uncover putative functional variation." (PMID 18053149, 2007). "Though we did not observe an association with breast cancer risk, results from our study provide a framework for future association studies of PRL pathway genes in relation to other diseases (such as Systemic Lupus Erythematosus) and for larger studies of plasma PRL levels." (PMID 18053149, 2007). "We sequenced the exons and splice-site regions of PRL and PRLR in germline DNA from 95 advanced breast cancer cases (19 of each racial/ethnic group)." (PMID 18053149, 2007). "We confirmed that prolactin was present in the T47D, MCF-7, MDA-MB-231 and Hs578T breast cancer cell lines." (PMID 15213724, 2004). "The correlation between prolactin (PRLR) and oestrogen (ER) or progesterone receptors (PgR) in breast cancer and a possible prognostic significance of PRLR at 10 year follow-up have been investigated in the Naples (GUN) adjuvant trial." (PMID 2223582, 1990).